FAM78B (family with sequence similarity 78 member B)
Tractability: PROTAC: its protein half-life has been measured.
Gene: Protein-coding gene on chromosome 1 (166,057,426 to 166,167,001, reverse strand). Ensembl gene ENSG00000188859.
Subcellular location (Human Protein Atlas): Golgi apparatus; Vesicles
Genetic constraint (gnomAD): Loss-of-function variants: 10 observed, 18.89 expected, observed/expected ratio (o/e) 0.53, 90% interval 0.33 to 0.9. The upper end of that interval is the gene's LOEUF score, 0.9, which puts it in group 3 of 6, group 1 being the genes least tolerant of losing a copy. Missense variants: 283 observed, 346.55 expected, observed/expected ratio (o/e) 0.82, 90% interval 0.74 to 0.9. Synonymous variants: 135 observed, 133.15 expected, observed/expected ratio (o/e) 1.01, 90% interval 0.88 to 1.17.
Homologues: Orthologues: chimpanzee FAM78B (100% identical), guinea pig FAM78B (100% identical), macaque FAM78B (100% identical), mouse Fam78b (100% identical), pig FAM78B (100% identical), rabbit FAM78B (100% identical), rat Fam78b (100% identical), tropical clawed frog fam78b (93% identical), zebrafish fam78bb (83% identical), zebrafish fam78ba (80% identical). Paralogues in human: FAM78A (72% identical).
Diseases named in the same sentence as FAM78B in open-access papers:
FAM78B is named in the same sentence as 3 diseases in open-access papers, as found by Europe PMC text mining. Sharing a sentence is not in itself a finding about the gene and the disease. The quoted sentences say what the papers report.
type 2 diabetes (2 papers, 2011 to 2015). "FAM78B is located at 1q24.1, which has previously been suggested to harbor susceptibility loci for hypertension and type 2 diabetes mellitus, although the function of the gene remains unclear." (PMID 25813534, 2015). "One region, upstream of the gene FAM78B, contains three binding sites for the transcription factor PPARG and two binding sites for HNF1A, both previously implicated in the pathology of type 2 diabetes." (PMID 22216000, 2011).
FAM78B also shares sentences with these, for which no sentence is quoted: Hypertension (1 paper); type 2 diabetes mellitus (1).